INS (insulin)
Diseases named in the same sentence as INS in open-access papers (continued):
Sharing a sentence is not in itself a finding about the gene and the disease.
diabetes (continued). "Diabetes mellitus (DM) is one of the most serious chronic diseases characterized by a chronic hyperglycemia resulting from defects in insulin secretion and/or insulin action." (PMID 30228829, 2018). "We aimed to determine the efficacy of a basal-bolus insulin protocol in hospitalized patients with diabetes treated with glucocorticoids." (PMID 30373567, 2018). "The most frequent type of diabetes is type 2 (T2DM) or independent insulin, characterized mainly by chronic hyperglycemia and insulin resistance in peripheral tissues." (PMID 29924854, 2018). "Type 2 diabetes mellitus (T2DM) is a disease with glucose and lipid metabolism disorder caused by the decrease of insulin sensitivity or β cells dysfunction, accounting for about 90% of all the patients with diabetes." (PMID 29534510, 2018). "longum can delay the onset of STZ-induced diabetes, possibly by affecting the insulin signalling pathway." (PMID 30662733, 2018). "Islet transplantation is a cellular replacement therapy used to treat severe diabetes mellitus in patients who are unable to control their blood glucose levels, even with intensive insulin treatment." (PMID 29735923, 2018). "In relation to factors that influenced its value to patients, respondents were unsure about gender, insulin regimen and hospital admissions, but more confident with regard to parental support, age and previous diabetes education." (PMID 28694992, 2018). "Some participants cited exercise benefits specifically related to diabetes such as lower blood glucose and insulin requirements." (PMID 29371269, 2018). "Insulin injection technique is part of diabetes education and essential for achieving optimal diabetes control." (PMID 30498521, 2018). "The relationship between insulin action and age is confounded by their own disease status such as obesity and diabetes." (PMID 30211231, 2018). "We aimed to compare efficacy, safety, and quality of treatment satisfaction of human and premixed analogue insulin among 3264 patients (53.58% women) with type 2 diabetes mellitus (T2DM) in a real-life environment." (PMID 29755520, 2018). "The Group 1 (whose clinical inertia during a period of 2 years of insulin therapy was studied) had 60.7% females, age of 65.8 ± 10 years, clinical diabetes duration of 18.6 ± 7.5 years and 10.6 ± 6.6 years of insulin therapy." (PMID 30386438, 2018). "To date, patients’ average (±standard deviation) age is 60.8 ± 10.3 years, average duration of diabetes 15.8 ± 7.9 years and average duration of insulin usage 9.4 ± 7.5 years." (PMID 29682315, 2018). "It is therefore reasonable to deduce that the disruptions to podocyte insulin signaling, occurring in conditions of diabetes and systemic insulin resistance, directly contribute toward disease, particularly in the early stages of DKD development." (PMID 30524379, 2018). "Patients with CAN progression were older; had a longer duration of diabetes; used more insulin; and had a higher level of HbA1c, fasting plasma glucose, LDL-cholesterol, and urinary albumin excretion." (PMID 30071872, 2018). "A number of new studies have pointed to the potential for conversion of non-β islet cells in to insulin-producing β-cells to replenish β-cell mass as a means to treat diabetes." (PMID 29534517, 2018). "In many individuals with insulin-treated diabetes, their attempts to achieve their glycemic targets are associated with frequent and/or severe hypoglycemia (SH)." (PMID 29707584, 2018). "Among insulin regimens, basal and premixed insulin have been widely used for insulin therapy of type 2 diabetes mellitus (T2DM)." (PMID 30420835, 2018). "Created and banked following cGMP guidelines, SR1423 is a candidate cell line for the production of insulin-producing cells useful for the treatment of diabetes." (PMID 30183752, 2018).
diabetes (continued). "This large multicentric observational study highlights that in outpatients with diabetes on basal-bolus insulin regimen, the amount of basal insulin is usually less than 50% of the total daily dose." (PMID 30918874, 2018). "Insulin has been widely used for blood glucose management in people with diabetes since its extraction and identification in 1921 by Banting and coworkers." (PMID 30116732, 2018). "Generally, the majority of the respondents in this study demonstrated poor knowledge about diabetes and insulin use, with the majority scoring below the mean for each knowledge category (mean DKT score 10.40 ± 2.8)." (PMID 30050608, 2018). "Other disease and therapy-related complications included 11 (14%) who had an admission-requiring infection, and 9 (12%) who developed diabetes mellitus - of these, one required treatment with insulin, six required oral agents, and two were diet-controlled." (PMID 30115013, 2018). "It is a challenge for many people with diabetes to estimate the appropriate insulin dose that correctly reflects the size and content of the meal, the pre-prandial glucose level and the expected level of physical activity." (PMID 29690520, 2018). "Specifically, diabetes patients from large households were more likely to receive oral antiglycaemic agents or insulin (OR = 1.1804 and 1.4037)." (PMID 30687763, 2018). "Insulin therapy is the primary means of controlling glycaemia in CFRD but its role in -pre-diabetes is less clear." (PMID 30021636, 2018). "One month after transplantation the patient developed diabetes requiring treatment with repaglinide quickly replaced with insulin to obtain an acceptable glycemic control (HbA1c 52 mmol/mol)." (PMID 30526503, 2018). "Type 1 diabetes mellitus (T1DM) is an organ-specific autoimmune disease in which the insulin-producing pancreatic β cells are destroyed by the immune system." (PMID 30214426, 2018). "Hypoglycaemia remains the most common metabolic adverse effect of insulin and sulfonylurea therapy in diabetes." (PMID 29417183, 2018). "In another study on young people with T1D, it was found that social media use allowed patients to gain knowledge and information about diabetes and interact when making their daily insulin adjustments." (PMID 30097421, 2018). "Both alpha and beta cell function were evaluated in 15 sub-Saharan Africans with ketosis-prone diabetes (KPD) who were insulin free and normoglycemic and 15 matched normal control patients by Choukem and colleagues in Paris." (PMID 30280274, 2018). "The prevalence of clinical inertia during insulin therapy in a group of T2DM followed at a tertiary public Diabetes Center with limited pharmacologic armamentarium was between 56.2 and 65.8%." (PMID 30386438, 2018). "In conclusion, FPG was most strongly associated with incident diabetes, followed by 2hPG, HbA1c, HOMA-IR and fasting insulin." (PMID 29018885, 2018). "Type 2 diabetes mellitus is a disease where the body either produces little insulin / ceases to produce insulin, or becomes progressively resistant to its action." (PMID 30522526, 2018). "After a diagnosis of diabetes, all patients started insulin therapy and all except four are still on insulin with variable glycaemic control." (PMID 29450569, 2018). "Knowledge about regional differences in insulin absorption rates helps clinicians and people with diabetes adjust insulin therapy according to specific conditions." (PMID 30116732, 2018). "The macronutrient composition of the diet has been shown to play a significant role in satiety, gut hormone secretion, glucose metabolism, and insulin secretion in healthy adults and in subjects with type 2 diabetes mellitus (T2DM)." (PMID 30213037, 2018). "There are many factors that affect the onset of the diabetes complication HU: i) multiple exposure to hypoglycaemic episodes, ii) individuals with a longer duration of diabetes and iii) insulin therapy." (PMID 30417151, 2018).
diabetes (continued). "Continuous subcutaneous insulin infusion (CSII) therapy by insulin pumps has become a widely used treatment in patients with type 1 diabetes mellitus (TIDM)." (PMID 29974056, 2018). "Hypoglycemia remains a common side effect with insulin-treatment and strategies to optimize therapy and reduce hypoglycemia occurrence in diabetes patients are required." (PMID 29433560, 2018). "While these models are extremely useful for understanding diabetes related phenomena such as body weight change, glucose-insulin dynamics, and insulin resistance, they are limited by analyzing these aspects in isolation." (PMID 29444133, 2018). "Diabetes is a metabolic syndrome characterized by hyperglycemia resulting from defects in insulin secretion, insulin action, or both." (PMID 30034976, 2018). "We showed that insulin treatment is associated with higher IGF1R and p-mTOR tumor expression in women with diabetes." (PMID 29486734, 2018). "It was clinically tested in a pilot study on 62 overweight or obese insulin-resistant adults who received a 24-week “virtual diabetes prevention” program, with human coaching." (PMID 30317460, 2018). "Another qualitative study focusing on care coordination for insulin initiation in patients with diabetes explored different clinician perceptions of roles as they pertained to developing relationships with clear communication, trust, and respect." (PMID 30463310, 2018). "There were no significant between-group differences in socio-demographics, duration of diabetes, oral antidiabetic drug use, insulin use and glycemic profile." (PMID 29970112, 2018). "There are two predominant types of diabetes; type 1 diabetes (T1D) is characterized by impaired insulin production and insulinopenia as a primary result of an autoimmune response against pancreatic β-cells." (PMID 30443826, 2018). "CAMK1, GLUT1/SLC2A1 and GLUT3/SLC2A3 genes were involved in glucose and insulin metabolism that played vital role in development of obesity and diabetes." (PMID 29876008, 2018). "Significantly more women with IGT and diabetes had a family history of diabetes; in addition, they more frequently needed insulin for control of GDM during pregnancy, compared to normoglycemic women." (PMID 30186874, 2018). "[if the medication being missed is] related to her insulin...and her blood sugars aren’t controlled, [then] the general impression probably is that her blood sugars aren’t controlled and her diabetes isn’t controlled." (PMID 30327290, 2018). "This group of users would primarily use telehealth for lifestyle and behavior change to manage their diabetes in contrast to insulin users who would primarily use telehealth for monitoring and adjusting insulin treatment." (PMID 29940936, 2018). "Eleven patients with pancreatic exocrine insufficiency were given daily pancreatic enzyme replacement therapy and 4 patients with new-onset diabetes were given insulin or oral hypoglycemic drugs." (PMID 29688844, 2018). "Her parents are dedicated to her daily diabetes management and are very compliant with tasks, such as injecting insulin, testing blood glucose, supervising diet intake, and correcting hyperglycemia." (PMID 29682577, 2018). "On the other hand homozygous tg/tg mice displayed diabetes, dyslipidemia, decreased insulin, elevated ALT, AST levels and destroyed islet structure." (PMID 29348618, 2018). "Islets of db/db mice presenting with uncontrolled diabetes were assessed in terms of morphological structure and insulin, glucagon, and glutaredoxin 5 expression." (PMID 29593651, 2018). "Diabetes mellitus (DM) is a common metabolic syndrome characterized by hyperglycemia due to insulin resistance or insulin secretion impairment." (PMID 29614759, 2018). "After the addition of small traces of metals, additive effects of vanadium were found, while manganese showed additive effects with insulin in vitro in animals with diabetes." (PMID 30513929, 2018).
diabetes (continued). "Altering insulin resistance and insulin secretion-related gene expression will make the diabetes model more closely mimic the pathology of diabetes." (PMID 29682407, 2018). "In Salten, Norway, around 80% of insulin-treated patients reported visits to specialist services regarding their diabetes during 2014 (unpublished data from the Rosa4 study, communicated by TCL)." (PMID 30404766, 2018). "Antidiabetic drugs (oral hypoglycemic agents or insulin) represented an expenditure of about €1.1 billion in 2012, i.e., one-half (49%) of all diabetes-specific expenditure (€2.3 billion)." (PMID 28190188, 2018). "Glucagon‐like peptide‐1 (GLP‐1) has aroused considerable interest as a novel therapeutic target for diabetes mellitus because it stimulates insulin secretion." (PMID 29659121, 2018). "In patients with diabetes mellitus, the promotion of glucose uptake into cells by insulin and consequent activation of fatty acid synthesis are essential for the reduction of blood glucose." (PMID 30258609, 2018). "Pleiotropic benefits like improvement in endothelial function and insulin sensitivity show its promise in patients with comorbidities like diabetes." (PMID 29887996, 2018). "The incidence of diabetes mellitus in the AI population was significantly higher than the general population, as was the number of diabetic patients requiring insulin." (PMID 30283862, 2018). "The IVGTT is an assessment of the first-phase insulin response to glucose for diagnosing glucose intolerance or overt diabetes in humans." (PMID 29677106, 2018). "They believed insulin-related training was important, but they also wanted ongoing support from a diabetes specialist." (PMID 29788908, 2018). "Both clinical and experimental data suggest that insulin sensitizers have a renoprotective role in patients with diabetes as well as in experimental animal models of diabetes." (PMID 29686650, 2018). "Flash glucose monitoring (FGM) or sensing technology is a new tool used over CGM or SMBG for glucose monitoring in insulin-treated T2DM patients (FGM is a new tool for CGM in patients with diabetes)." (PMID 29527102, 2018). "In the Australian Fremantle Diabetes Study, 15% patients had switched to insulin treatment within 5 years of follow-up." (PMID 30327785, 2018). "A significant negative correlation was found between the PAID score and the adherence score (r = − 0.3), duration of diabetes since diagnosis (r = − 0.172), and the duration of insulin therapy (r = − 0.239)." (PMID 29520741, 2018). "On admission, 37% of the diabetes group were receiving insulin, 33% were taking metformin and 33% were taking sulphonylureas." (PMID 30202020, 2018). "Pathological effects of signal peptide mutations have been characterized already in other genes (diseases) such as insulin (diabetes), COL10A1 (Schmid-type metaphyseal chondrodysplasia, MCDS), and COL5A1 (classical Ehlers–Danlos Syndrome, cEDS)." (PMID 29101475, 2018). "Type-2 diabetes mellitus (diabetes) is a metabolic disease characterized by chronic hyperglycemia resulting from defects in insulin secretion and/or insulin resistance." (PMID 30408096, 2018). "Type 2 Diabetes Mellitus (T2DM) is a progressive condition in which a person’s body becomes resistant to the normal effects of insulin and/or slowly loses the ability to produce enough insulin in the pancreas causing elevations in blood glucose." (PMID 30165844, 2018). "This type of diabetes cannot be cured effectively with oral medications alone and the patients are required insulin therapy." (PMID 30459809, 2018). "In one survey, there was disagreement regarding who was responsible for intensification but the majority of both diabetes specialists and primary care physicians agreed that doctors in primary care should become more involved in managing insulin." (PMID 29788908, 2018).
diabetes (continued). "The pharmacological activators of PPARγ include thiazolidinediones (TZDs), which are insulin sensitizers used in the treatment of type 2 diabetes mellitus (T2DM), despite some drawbacks." (PMID 30060458, 2018). "Megaloblastic anemia and diabetes were diagnosed at 8 months and was successfully treated with vitamin and insulin prescription." (PMID 29379566, 2018). "People with postprandial hyperglycaemia, such as pre-diabetes or impaired insulin sensitivity, are advised to consume low GI foods and a low GI diet has been recommended to reduce the risk of type 2 diabetes mellitus (T2DM) and obesity." (PMID 29419785, 2018). "Diabetes mellitus (DM) is a chronic metabolic disorder resulting from insufficient insulin secretion or insulin dysfunction." (PMID 30424024, 2018). "In particular with diabetes, Nrf2 activation protects pancreatic β-cells against various insults thereby maintain glucose homeostasis and also increase the insulin sensitivity." (PMID 29572460, 2018). "During the present perioperative management, in consideration of diabetes, an electrolyte solution containing rapid acting insulin was prepared according to the sliding scale of our hospital for blood glucose values above 200 mg/dL." (PMID 30526578, 2018). "Severe hypoglycaemia can occur in people with diabetes mellitus who take insulin and other anti-diabetic treatments." (PMID 29445964, 2018). "The participants not followed up were similar to the participants in the study except they were older at transfer from insulin to sulfonylureas and younger at diabetes diagnosis." (PMID 29880308, 2018). "Diabetes mellitus presented after the surgery due to partial pancreatectomy and our patient continues to take single-dose glargine insulin treatment." (PMID 29513222, 2018). "Of note, recombinant FGF21 improved glucose and triglyceride levels and insulin sensitivity in an animal model of diabetes." (PMID 29385702, 2018). "The long-term follow-up UKPDS and DCCT stressed the importance of intensive glycemic control with insulin, especially from the early stages of diagnosis of diabetes." (PMID 29508275, 2018). "This study aims to evaluate clinical inertia of insulin treatment intensification in a group of T2DM patients followed at a tertiary public Diabetes Center with limited pharmacologic armamentarium (Metformin, Sulphonylurea and Human Insulin)." (PMID 30386438, 2018). "In Iraqi-born participants fasting glucose, 2-h glucose, fasting insulin, 2-h insulin, C-peptide and HbA1c increased with increasing number of family members with diabetes." (PMID 29274011, 2018). "Decreased insulin secretion and/or its responsiveness to the tissues, leading to dysfunctions of protein, lipid, and carbohydrate metabolism is characterized as diabetes mellitus." (PMID 30602713, 2018). "As for patients with positive IAA, they were more likely to have insulin treatment with longer duration of diabetes, higher level of BMI, and lower level of postprandial C peptide." (PMID 29887833, 2018). "From our data, few of these older adults participate in the types of aerobic and strength training that can lead to benefits in adults with diabetes, such as insulin sensitivity and glucose control." (PMID 29662686, 2018). "Our method identifies use of insulin and duration of diabetes as novel interpretable features to assist with clinical decisions in identifying the high-risk populations for diabetic retinopathy." (PMID 30367589, 2018). "Diabetes mellitus is a chronic metabolic disorder marked by high blood glucose levels resulting from defects in insulin secretion, insulin action, or both." (PMID 30123269, 2018). "Type 1 diabetes mellitus results from the body’s failure to produce insulin, and requires the person to inject insulin or wear an insulin pump." (PMID 29324896, 2018).